RAD51C (RAD51 paralog C)
Diseases named in the same sentence as RAD51C in open-access papers (continued):
Sharing a sentence is not in itself a finding about the gene and the disease.
ovarian carcinoma (continued). "Monoallelic mutations in five FA genes (BRCA1, BRCA2, PALB2, RAD51C, BRIP1) have now been confirmed to predispose to breast or ovarian cancer while biallelic mutations in these genes cause FA3." (PMID 31467304, 2019). "Deficiency in the canonical RAD51 paralogs, such as RAD51C and RAD51D, are linked to familial breast and ovarian cancer predisposition." (PMID 31665741, 2019). "RAD51C was included in the genetic analysis because, at the time of pretest counseling, the patient reported that her aunt had been diagnosed with ovarian cancer, which subsequently was determined to be cervix cancer." (PMID 31125277, 2019). "Mutations in the human RAD51 paralogs (RAD51B, RAD51C, RAD51D, XRCC2, XRCC3, and SWSAP1) are found in a subset of breast and ovarian cancers." (PMID 30551670, 2018). "Nevertheless, other studies have indicated that mutations in RAD51C and RAD51D contribute to the risk of both breast and ovarian cancer, and that RAD50 is an intermediate-risk breast cancer susceptibility gene." (PMID 29566657, 2018). "An increased risk of breast or ovarian cancer is associated with monoallelic mutations in a subset of these genes (BRCA1, BRCA2, BRIP1, PALB2, RAD51C)." (PMID 28874143, 2017). "In this study, we have genotyped 68 MBC patients for the known breast or ovarian cancer associated mutations in the Finnish population in CHEK2, PALB2, RAD51C, RAD51D, and FANCM genes." (PMID 28874143, 2017). "In the Finnish population, recurrent founder mutations have been observed in many of the known breast and ovarian cancer susceptibility genes, including the RAD51 paralogs RAD51C and RAD51D." (PMID 27149063, 2016). "Several FA genes are also breast and ovarian cancer susceptibility genes (FANCD1/BRCA2, FANCJ/BRIP1, FANCN/PALB2, FANCO/RAD51C, and FANCS/BRCA1)." (PMID 26430909, 2015). "At least 5 of the 17 known FA genes, D1/BRCA2, J/BRIP1, N/PALB2, O/RAD51C and S/BRCA1, are well-established breast and/or ovarian cancer susceptibility genes." (PMID 26085575, 2015). "Deleterious germline mutations in the RAD51C and RAD51D genes confer an increased risk of ovarian cancer whereas common polymorphisms in the RAD51B gene are associated with male and female breast cancer." (PMID 25918678, 2015). "RAD51C R258H and L138F mutants were identified in FA and breast/ovarian cancer patients, respectively." (PMID 26354865, 2015). "While germline mutations in RAD51C and RAD51D are associated with high ovarian cancer risk and RAD51B polymorphisms with breast cancer, the contribution of RAD51, XRCC3, and XRCC2 is more unclear." (PMID 25918678, 2015). "Germline mutations in at least four Fanconi Anemia genes (BRCA2, PALB2, RAD51C, BRIP1) have thus far been found to contribute to the inherited risk of breast or ovarian cancer." (PMID 24465539, 2014). "The present study analysed the five RAD51 paralogs (RAD51B, RAD51C, RAD51D, XRCC2, XRCC3) to estimate their contribution to breast and ovarian cancer predisposition." (PMID 24139550, 2013). "Mutation analyses in further genes of RAD51 paralogs have uncovered RAD51C and RAD51D as susceptibility genes in hereditary breast and ovarian cancer families." (PMID 24025454, 2013). "Two other genes involved in FA and related to breast or ovarian cancer predisposition are PALB2/FANCN and RAD51C/FANCO." (PMID 22778927, 2012). "Screening for pathogenic variants in breast and ovarian cancer genes BRCA1/2, CHEK2 and RAD51C is common practice for individuals from high-risk families." (PMID 23239986, 2012). "Screening for pathogenic mutations in breast and ovarian cancer genes such as BRCA1/2, CHEK2 and RAD51C is common practice for individuals from high-risk families." (PMID 23239986, 2012). "Future studies investigating larger, multi-ethnic populations of ovarian cancers, and that include sampling of family members, are needed to better understand the role of RAD51C in ovarian cancers and HBOC." (PMID 21980511, 2011).
ovarian carcinoma (continued). "To further investigate the role of RAD51C as an HBOC predisposition gene, we performed complete sequencing of RAD51C to screen for mutations in 286 BRCA1- and BRCA2-negative breast and/or ovarian cancer cases with a family history of breast and ovarian cancer." (PMID 21980511, 2011). "Several likely pathogenic RAD51C mutations have been identified in BRCA1- and BRCA2-negative breast and ovarian cancer families." (PMID 21980511, 2011). "While consensus was not reached for recontact of individuals with a GPV in intermediate penetrance CSGs (RAD51C and RAD51D) with respect to breast cancer risk management, consensus was reached for recontact for these genes (and BRIP1) with respect to ovarian cancer risk management." (PMID 41159931, 2025). "RAD51C/RAD51D-mutated breast and ovarian cancers show HRD profiles predictive of PARPi response." (PMID 40864792, 2025). "Our study differs from the research conducted by Manchanda et al31 on the cost-effectiveness of population-based testing for BRCA1, BRCA2, RAD51C (OMIM 602774), RAD51D (OMIM 602954), BRIP1 (OMIM 605882), and PALB2 mutations for preventing breast and ovarian cancer in the following ways." (PMID 38353949, 2024). "Given the rarity of RAD51C mutations, the risk and treatment of metachronous breast cancer after the diagnosis of ovarian cancer in RAD51C mutation carriers is not clear, especially for those who have received PARPi treatment." (PMID 38360632, 2024). "Besides, 9 out of 16 ovarian cancer cases (56.3%) harboured genetic variants: six BRCA1 (37.5%), two RAD51C (12.5%) and in one case BRCA2 (6.25%)." (PMID 39148954, 2024). "We aimed to perform a comprehensive molecular analysis of a large cohort of patients with RAD51C/D untreated primary breast cancer and ovarian cancer to describe the prevalence of HRD by different biomarkers and investigate the role of the germline alterations in tumorigenesis." (PMID 38648056, 2024). "However, BRCA1 and RAD51C promoter hypermethylation have been reported only in sporadic breast and ovarian cancer cases." (PMID 39406235, 2024). "RAD51C promoter hypermethylation was observed in one breast and two ovarian cancer samples." (PMID 39406235, 2024). "Moreover, a recent meta-analysis provided evidence supporting the pathogenicity of BRIP1, RAD51C, and RAD51D mutations in relation to ovarian cancer, cumulatively contributing to ~2% of ovarian cancer cases." (PMID 37444530, 2023). "In addition, BRCA1/2, ATM, BRIP1, PALB2, RAD51C, and RAD51D gene mutations are reported to be associated with high risk of ovarian cancers, and from the results of tumor tissue, it is easy to further determine their genetic status." (PMID 35186721, 2022). "Silencing of RAD51C expression has also been shown to make tumor cells more sensitive to PARPi in vitro and has also been replicated in clinical trials for patients with ovarian cancer who had an increased response rate to rucaparib." (PMID 35626165, 2022). "Our findings support the role of inherited variants in RAD51C and RAD51D in ovarian cancer." (PMID 35565380, 2022). "An analysis of the presence of mutations in BRCA1, BRCA2, RAD51C, PALB2, and CHEK2 with the age of onset of ovarian cancer revealed a lower age of ovarian cancer diagnosis in BRCA1 mutation carriers than in non-carriers of BRCA1 (51.6 vs. 57.6, p = 2.97 × 10−11)." (PMID 33670479, 2021). "In addition, analysis of the promoters of BRCA1 and RAD51C, whose methylation has been shown to be associated with HRD in breast and ovarian cancer, revealed that UCS10 and UCS12 displayed RAD51C promoter hypermethylation." (PMID 33021035, 2021). "Mutations in RAD51C, PALB2, and CHEK2 genes were previously analyzed in ovarian cancers." (PMID 33670479, 2021).
ovarian carcinoma (continued). "For BRIP1 and RAD51C, the median age at ovarian cancer diagnosis was after 60 years." (PMID 33926482, 2021). "The level of ovarian cancer risk conferred by these mutations is relatively high, indicating that after BRCA1 and BRCA2, the BRIP1, RAD51C, and RAD51D genes are the most important ovarian cancer risk genes, cumulatively contributing to ~ 2% of ovarian cancer cases." (PMID 32359370, 2020). "Women with mutations in moderate penetrance genes, such as RAD51C, RAD51D, and BRIP1 mutations, have a lifetime risk of 5.2–12% and may benefit from ovarian cancer screening." (PMID 32098383, 2020). "Ovarian cancers have a high frequency of homologous recombination deficiency (HRD) due to germline or somatic mutations in the BRCA1 or BRCA2 genes, methylation of the BRCA1 or RAD51C promoter regions or other genetic alterations." (PMID 32256521, 2020). "Additionally, pathogenic alterations in PALB2, ATM, CHEK2, and NBN are correlated with an increased risk for breast cancer and/or other cancers, whereas other genes such as BRIP1, RAD51C, and RAD51D are associated with an increased ovarian cancer risk." (PMID 32733558, 2020). "Segregation analysis from large international consortia has been used to calculate ovarian cancer risks in RAD51C, RAD51D, and PALB2, and could be applied to other moderate risk ovarian cancer genes." (PMID 33086730, 2020). "RAD51C is important in DNA repair and carriers of pathogenic RAD51C variants have increased risk of hereditary breast and ovarian cancer syndrome (HBOC), an autosomal dominant genetic predisposition to early onset breast and/or ovarian cancer." (PMID 31782267, 2020). "RAD51C is important in DNA repair and individuals with pathogenic RAD51C variants have increased risk of hereditary breast and ovarian cancer syndrome (HBOC), an autosomal dominant genetic predisposition to early onset breast and/or ovarian cancer." (PMID 31782267, 2020). "To more precisely estimate the ovarian cancer risk attributed to BRIP1, RAD51C, and RAD51D mutations, we performed a meta-analysis based on a comparison of a total of ~ 29,400 ovarian cancer patients from 63 studies and a total of ~ 116,000 controls from the gnomAD database." (PMID 32359370, 2020). "Germline mutations in both RAD51C and RAD51D were identified in families with ovarian cancer." (PMID 30672100, 2019). "The family history of the patient harboring the c.890_899del mutation in RAD51C has no confirmed ovarian cancer diagnosis, but includes a relative with gynecological cancer deceased at young age." (PMID 29659569, 2018). "Along with BRCA1 (FANCS) and BRCA2 (FANCD1), involved in hereditary breast/ovarian cancer (HBOC) syndrome, three other members of the FANC family have been associated with an increased risk of development of BrCa and/or ovarian cancer (OvCa), namely BRIP1 (FANCJ), PALB2 (FANCN) and RAD51C (FANCO)." (PMID 29659569, 2018). "Several FA genes (FANCD1/BRCA2, FANCN/PALB2, FANCJ/BRIP1, FANCO/RAD51C, and FANCS/BRCA1) are high- or moderate-risk breast or ovarian cancer susceptibility genes and previous studies have connected also heterozygous FANCM mutations with breast cancer predisposition." (PMID 28702895, 2017). "Additionally, other genes involved in HR including BRIP1, RAD51C and RAD51D have been implicated in genetic susceptibility to ovarian carcinoma." (PMID 29228718, 2017). "Rare pathogenic mutations in RAD51 paralogs RAD51C and RAD51D have been identified in breast and ovarian cancer families and confer a high risk specifically for ovarian cancer whereas a homozygous missense mutation in RAD51C (FANCO) was found in a Fanconi anemia patient." (PMID 27149063, 2016).
ovarian carcinoma (continued). "For model development, genetic data will involve genetic testing of high penetrance genes associated with hereditary breast and ovarian cancer, BRCA1 and BRCA2, as well as lower penetrance genes associated with ovarian cancer susceptibility, BRIP1, RAD51C and RAD51D." (PMID 25391615, 2015). "Promoter methylation of Rad51C has been shown in breast and ovarian cancer patients." (PMID 25669972, 2015). "Interestingly, one Fanconi anemia patient has been found to carry a homozygous truncating XRCC2 mutation while biallelic mutations in four breast and ovarian cancer susceptibility genes, BRCA2, BRIP1, PALB2, and RAD51C, are associated with Fanconi anemia." (PMID 25918678, 2015). "Recent studies have conferred that the RAD51C and RAD51D genes, which code for the essential proteins involved in homologous recombination, are ovarian cancer (OC) susceptibility genes that may explain genetic risks in high-risk patients." (PMID 26057125, 2015). "In addition, RAD51C and RAD51D germline truncations are positively correlated with increased somatic mutation frequencies in ovarian cancer." (PMID 26689913, 2015). "Breast and ovarian cancer share susceptibility genes such as BRCA1/2 and RAD51C, making it likely that they may share mechanisms underlying cancer risk." (PMID 25389105, 2014). "Deleterious and missense mutations of RAD51C have recently been suggested to modulate the individual susceptibility to hereditary breast and ovarian cancer and unselected ovarian cancer, but not unselected breast cancer (BrC)." (PMID 25343521, 2014). "First, highly penetrant mutations were identified in the RAD51C gene in families with both breast and ovarian cancer (1.3%) but not in families with breast cancer only." (PMID 23344037, 2013). "Identification of families with mutations in the RAD51B, RAD51C or XRCC3 genes and genetic testing of family members could be used to estimate the associated breast and ovarian cancer risks." (PMID 24139550, 2013). "Biallelic or in the case of FA-B hemizygous mutations in any one of the underlying genes lead to FA, while monoallelic mutations in FANCD1 (BRCA2), FANCJ (BRIP1), FANCN (PALB2) or FANCO (RAD51C) increase the risk of carriers for developing breast and ovarian cancer." (PMID 23285130, 2012). "In the Finnish population, we have identified two founder mutations in RAD51C that increase the risk of ovarian cancer but not breast cancer in the absence of ovarian cancer." (PMID 23176254, 2012). "The mutations significantly increased the risk of ovarian cancer but not breast cancer in the absence of ovarian cancer family history, indicating RAD51C as the first moderate penetrance susceptibility gene for ovarian cancer." (PMID 23176254, 2012). "We recently sequenced the RAD51C gene in 277 Finnish breast and/or ovarian cancer families and identified two recurrent deleterious, protein truncating mutations c.837 + 1G > A and c.93delG and subsequently genotyped the mutations in a large series of breast and ovarian cancer patients and families." (PMID 23176254, 2012). "Indeed, RAD51C and RAD51D mutations have been specifically found in breast plus ovarian cancer families." (PMID 23300655, 2012). "In the current study, we screened for RAD51C mutations in a clinic-based set of women with breast and/or ovarian cancers in families with HBOC who had previously tested negative for BRCA1 and BRCA2 mutations." (PMID 21980511, 2011). "The small number of PALB2 mutations limits interpretation; however, RAD51C, RAD51D, and BRIP1 mutations were associated with both high rates of biallelic loss and high GIS, suggesting that these genes might be true drivers of HRD in ovarian cancer." (PMID 39695768, 2024).
ovarian carcinoma (continued). "Finally, germline mutations in Breast Cancer Gene 1 (BRCA1), Breast Cancer Gene 2 (BRCA2), BRCA1 interacting Protein 1 (BRP1), Partner and Localizer of BRCA2 (PALB2), RAD51 homolog C (RAD51C), RAD51 homolog D (RAD51D), and individuals with Lynch syndrome are susceptible to ovarian cancers." (PMID 37110218, 2023). "Consistently, a retrospective case-control analysis of ovarian cancer patients enrolled in the ARIEL2 and ARIEL3 trials suggested an increased incidence of tMN among patients carrying pathogenic variants in genes involved in homologous recombination pathway (BRCA1, BRCA2, RAD51C and RAD51D)." (PMID 37119509, 2023). "More recent studies have improved our understanding of inherited ovarian cancer risk beyond BRCA-related HBOC, and have allowed more detailed estimates of ovarian cancer risk for several homologous recombination (HR)-related genes with moderate-penetrance such as BRIP1, RAD51C/D, PALB2, and ATM." (PMID 35163487, 2022). "As studying French Canadians could facilitate the identification and interpretation of clinically relevant variants, we performed genetic analyses of RAD51C and RAD51D in this population comprised of cases with a family history of ovarian cancer or those who developed it at a young age." (PMID 35565380, 2022). "In addition, it is well known that some HRR genes such as BRCA1/2, ATM, BRAD1, BRIP1, PALB2, RAD51C, and RAD51D are associated with high risk of ovarian cancers, and tissue detection might be a good way to learn the germline status." (PMID 35186721, 2022). "The ovarian cancer risk was associated with mutations in BRCA1 (OR = 40.79, 95% CI: 18.67–114.78; p = 0.29 × 10−15), in BRCA2 (OR = 25.98; 95% CI: 1.55–434.8; p = 0.001), in RAD51C (OR = 6.28; 95% CI 1.77–39.9; p = 0.02), and in PALB2 (OR 3.34; 95% CI: 1.06–14.68; p = 0.06)." (PMID 33670479, 2021). "BRCA1 and BRCA2 encode proteins involved in recombinational repair of damaged DNA and it has been found that mutations in other genes involved in the repair of DNA damage by homologous recombination, including e.g., RAD51C, RAD51D, BRIP1, PALB2, and CHEK2 may be associated with ovarian cancer risk." (PMID 33670479, 2021). "Population panel testing for BRCA1/BRCA2/RAD51C/RAD51D/BRIP1/PALB2 gene mutations is the most cost-effective genetic-testing strategy in general-population women and can prevent thousands more breast and ovarian cancers than current clinical-criteria based approaches." (PMID 30400647, 2018). "Notably, we find that Fanconi anemia (FA)-like disorder and breast and ovarian cancer patient derived mutations of RAD51C fails to protect replication fork, exhibit under-replicated genomic regions and elevated micro-nucleation." (PMID 26354865, 2015). "A variant near RAD51C was genome-wide significant for tooth eruption; this gene has been implicated in a Fanconi anaemia-like disorder as well as in rare monogenic forms of breast and ovarian cancer, but not in tooth development." (PMID 23704328, 2013). "Recently, RAD51C, essential for homologous recombination repair, has been reported to be a rare hereditary breast and ovarian cancer susceptibility gene and several pathogenic RAD51C mutations have been identified in BRCA1- and BRCA2-negative hereditary breast and ovarian cancer families (HBOC)." (PMID 21980511, 2011). "Promoter hypermethylation of key HRR genes, especially BRCA1 and RAD51C, can silence gene expression and induce HRD, with prevalence reaching up to 60% in TNBC and 1–15% in ovarian cancer." (PMID 40864792, 2025). "BOADICEA V5’s newest version includes the effects of pathogenic variants (PVs), not restricted to BRCA1 and BRCA2 genes but also in PALB2, CHEK2, ATM, and BARD1 for the breast cancer model and RAD51D, RAD51C, and BRIP1 for the ovarian cancer model." (PMID 39590369, 2024).